RPA2 (replication protein A2)
Description:
As part of the heterotrimeric replication protein A complex (RPA/RP-A), binds and stabilizes single-stranded DNA intermediates that form during DNA replication or upon DNA stress. It prevents their reannealing and in parallel, recruits and activates different proteins and complexes involved in DNA metabolism. Thereby, it plays an essential role both in DNA replication and the cellular response to DNA damage. In the cellular response to DNA damage, the RPA complex controls DNA repair and DNA damage checkpoint activation. Through recruitment of ATRIP activates the ATR kinase a master regulator of the DNA damage response. It is required for the recruitment of the DNA double-strand break repair factors RAD51 and RAD52 to chromatin in response to DNA damage. Also recruits to sites of DNA damage proteins like XPA and XPG that are involved in nucleotide excision repair and is required for this mechanism of DNA repair. Also plays a role in base excision repair (BER) probably through interaction with UNG. Also recruits SMARCAL1/HARP, which is involved in replication fork restart, to sites of DNA damage. May also play a role in telomere maintenance. RPA stimulates 5'-3' helicase activity of BRIP1/FANCJ.
Synonyms: RP-A p32; RP-A p34; REPA2; RPA32
Tractability: Small molecule: a structure with a bound ligand is known. PROTAC: UniProt records ubiquitination sites on it; ubiquitination databases record sites on it; its protein half-life has been measured.
Gene: Protein-coding gene on chromosome 1 (27,891,524 to 27,914,746, reverse strand). Ensembl gene ENSG00000117748.
Subcellular location: Nucleus; Nucleus, PML body
Subcellular location (Human Protein Atlas): Nuclear bodies; Nucleoplasm
Pathways (Reactome):
DNA Repair: Dual Incision in GG-NER; Dual incision in TC-NER; Fanconi Anemia Pathway; Formation of Incision Complex in GG-NER; Gap-filling DNA repair synthesis and ligation in GG-NER; Gap-filling DNA repair synthesis and ligation in TC-NER; HDR through Homologous Recombination (HRR); HDR through Single Strand Annealing (SSA); PCNA-Dependent Long Patch Base Excision Repair; Presynaptic phase of homologous DNA pairing and strand exchange; Processing of DNA double-strand break ends; Recognition of DNA damage by PCNA-containing replication complex; Termination of translesion DNA synthesis; Translesion Synthesis by POLH; Translesion synthesis by POLI; Translesion synthesis by POLK; Translesion synthesis by REV1
Cell Cycle: Activation of ATR in response to replication stress; G2/M DNA damage checkpoint; Removal of the Flap Intermediate from the C-strand
Cellular responses to stimuli: HSF1 activation; Regulation of HSF1-mediated heat shock response
DNA Replication: Activation of the pre-replicative complex; Removal of the Flap Intermediate
Disease: Impaired BRCA2 binding to RAD51
Reproduction: Meiotic recombination
Gene Ontology:
Molecular function: damaged DNA binding; enzyme binding; G-rich strand telomeric DNA binding; protein binding; protein phosphatase binding; single-stranded DNA binding; ubiquitin protein ligase binding; telomeric DNA binding; DNA binding
Biological process: base-excision repair; DNA replication; double-strand break repair via homologous recombination; mismatch repair; mitotic G1 DNA damage checkpoint signaling; nucleotide-excision repair; protein localization to chromosome; regulation of DNA damage checkpoint; regulation of double-strand break repair via homologous recombination; telomere maintenance; DNA damage checkpoint signaling; DNA recombination; DNA repair
Cellular component: chromatin; chromosome, telomeric region; DNA replication factor A complex; nuclear body; nucleoplasm; nucleus; PML body; site of double-strand break
Genetic constraint (gnomAD): Loss-of-function variants: 19 observed, 27.73 expected, observed/expected ratio (o/e) 0.69, 90% interval 0.48 to 1. The upper end of that interval is the gene's LOEUF score, 1, which puts it in group 4 of 6, group 1 being the genes least tolerant of losing a copy. Missense variants: 264 observed, 323.97 expected, observed/expected ratio (o/e) 0.81, 90% interval 0.74 to 0.9. Synonymous variants: 106 observed, 116.34 expected, observed/expected ratio (o/e) 0.91, 90% interval 0.78 to 1.07.
Homologues: Orthologues: macaque RPA2 (99% identical), chimpanzee RPA2 (97% identical), pig RPA2 (91% identical), dog RPA2 (90% identical), mouse Rpa2 (89% identical), guinea pig RPA2 (87% identical), rabbit RPA2 (82% identical), rat Rpa2 (78% identical), tropical clawed frog rpa2 (67% identical), zebrafish rpa2 (57% identical). Paralogues in human: RPA4 (43% identical), STN1 (18% identical).
Diseases named in the same sentence as RPA2 in open-access papers:
RPA2 is named in the same sentence as 50 diseases in open-access papers, as found by Europe PMC text mining. Sharing a sentence is not in itself a finding about the gene and the disease. The quoted sentences say what the papers report.
breast carcinoma (9 papers, 2014 to 2023). "In the whole cohort, low RPA2 was associated with poor breast cancer-specific survival (BCSS) (P < 0.0001) and distant metastasis-free survival (DMFS) (P = 0.001)." (PMID 36997566, 2023). "For DNA CNV dataset, the PHACTR4 was associated with prostate, breast andcolon cancer, while RPA2 was associated with breast cancer." (PMID 36175944, 2022). "Of note, RPA2 overexpression is implicated in the general pathogenesis of cancer and its ectopic expression in breast cancer cells abrogates menin/NF-κB–p65 complex formation and unleashes the expression of NF-κB-regulated oncogenes." (PMID 34316690, 2020). "In ER + breast cancers that received endocrine therapy, low RPA2 was associated with poor BCSS (P = 0.003) implying that RPA2 could predict response to endocrine therapy." (PMID 36997566, 2023). "We the tested whether a similar approach would be feasible in RPA2 deficient breast cancer cells." (PMID 36997566, 2023). "MCM10 OE was able to increase RPA2 compared to controls in breast cancer patient biopsy and in MCF10A OE cells, which further induced high expression of downstream proteins ATR and CHEK1, supporting the possibility of increased ssDNA in MCM10 OE cells." (PMID 35813483, 2022). "In normal and breast cancer tissues, RPA2 expression was limited to the nuclei." (PMID 36997566, 2023). "Thus, valproic acid, a histone deacetylase inhibitor, and hydroxyurea, a ribonucleotide reductase inhibitor, synergistically sensitize breast cancer cells by perturbing RPA2 hyperphosphorylation and thus HR." (PMID 34316690, 2020). "We observed an analogous decrease in RPA2 hyperphosphorylation in MDA-MB231 breast cancer cells transiently depleted in PARG by siRNA and treated with 2 mM HU for 24 h, and this hyperphosphorylation was restored in the presence of a PARP inhibitor (data not shown)." (PMID 24906880, 2014). "Therefore, targeting of RPA2–menin interaction in breast cancer cells may be a promising therapeutic strategy." (PMID 34316690, 2020). "These genes were markedly differentially expressed in breast cancer tissues compared to normal tissues except for RPA1 and RPA2." (PMID 36533385, 2023). "However, in further DNA damage analysis, RPA2 (replication protein A2) and PICH (PLK1-interacting checkpoint helicase), the factors involved in DNA replication, were stained in breast cancer cells." (PMID 34123836, 2021).
ovarian carcinoma (7 papers, 2015 to 2025). A malignant neoplasm originating from the surface ovarian epithelium. "p-RPA2 foci reflect replication stress and can be quantified in patient-derived ovarian cancer samples." (PMID 40392598, 2025). "Overexpression and phosphorylation of RPA2 were reported in several cancers, including esophageal, bladder, and ovarian cancers." (PMID 37810966, 2023). "Recent research has also shown that alterations in the genome region of CTNNB1 and RPA2 were closely related to the occurrence of ovarian cancer." (PMID 25803614, 2015). "Additionally, using samples from multiple cohorts of patients with ovarian cancer, we show that HR-proficient, p-RPA2-high HGSCs had significantly better responses to platinum chemotherapy and PARP inhibitors than HR-proficient, p-RPA2-low HGSCs." (PMID 40392598, 2025). "In addition, CCNH was related to the promotion of cancer cell migration, and RPA2 expression was an independent predictor of adverse outcome in ovarian cancer." (PMID 35769257, 2022). "The replication stress marker, phospho-RPA2, predicts response to platinum chemotherapy and PARP inhibitors in homologous recombination-proficient ovarian cancer, offering a biomarker to improve patient outcomes." (PMID 40392598, 2025). "Silencing KRCC1 in the OV90 ovarian cancer cells and in the U2OS osteosarcoma cells significantly increased RPA2 foci formation by ∼6- and 8-fold, respectively, compared to the control cells." (PMID 36243983, 2022).
Stroke (4 papers, 2015 to 2018). Sudden impairment of blood flow to a part of the brain due to occlusion or rupture of an artery to the brain. "SEREX identified RPA2 as the antigen associated with ischemic stroke and serum auto-antibodies against RPA2 elevates in stroke patients." (PMID 25890248, 2015). "Of these antigens, replication protein A2 (RPA2) was determined to be the antigen associated with stroke (P < 0.05) by ELISA with 2nd screening and validation cohort." (PMID 25890248, 2015). "To validate the elevated levels of RPA2-Abs in stroke patients and to identify the antigenic epitopes of RPA2, we further examined the RPA2-Abs levels using synthetic peptides in the independent validation cohort (n =78)." (PMID 25890248, 2015). "If the cut-off value of the bRPA2-132-Ab level was determined to be 0.334, the sensitivity and specificity of RPA2-Ab level for the diagnosis of stroke were 0.323 (95% CI: 0.209-0.453) and 1.00 (95% CI: 0.713-1.00), respectively." (PMID 25890248, 2015). "If the cut-off value of the RPA2-Ab level was determined to be 0.275, the sensitivity and specificity of the antibody level for the diagnosis of stroke were 0.703 (95% CI: 0.612-0.784) and 0.917 (95% CI: 0.730-0.990), respectively." (PMID 25890248, 2015). "We have recently reported novel atherosclerosis-related antibody markers, such as antibodies against RPA2 for stroke, antibodies against SOSTDC1 and TUBB2C for CI and DM, and antibodies against ATP2B4 and BMP-1 for atherosclerosis-related diseases, such as CI, CAD, DM and chronic kidney disease." (PMID 28936256, 2016). "Multifactorial logistic regression analysis showed that the increased levels of the RPA2 antibodies (RPA2-Abs) associated with stroke independent of other risk factors for stroke (P < 0.05)." (PMID 25890248, 2015). "And therefore, the RPA2-Abs might be a biomarker for the evaluation of stroke at risk rather than the stroke itself." (PMID 25890248, 2015). "We hypothesize that the RPA2-Abs might originate from the vascular lesion (i.e. atherosclerotic plaque) and that the RPA2-Abs might become a biomarker for the diagnosis of and, conceivably, for the prediction of stroke." (PMID 25890248, 2015).
atherosclerosis (3 papers, 2015 to 2018). A disease characterized by the build-up of fatty material and calcium deposition in the arterial wall resulting in partial or complete occlusion of the arterial lumen. "For example, autoantibodies, such as those against RPA2, ATP2B4, and TUBB2C have been identified as atherosclerosis and/or CI markers." (PMID 29464021, 2018).
colon cancer (3 papers, 2008 to 2021). "Genetic variations in DNA synthesis gene Rpa3 have been associated with susceptibility to carcinomas, whereas increased cancer expression of Rpa2 is associated with adverse outcome in colon cancer." (PMID 18706093, 2008). "High levels of RPA2 expression have been associated with adverse disease progression and it may also be a therapeutic potential target for treating colon cancer itself, while FOS gene expression has been found to be associated with progression of pancreatic cancer tumors." (PMID 34585118, 2021). "ATR, RPA2 and TRX have been validated before as hnRNP A18 targets in colon cancer cells and are used here as positive controls for hnRNP A18 binding to targeted transcripts in melanoma cells." (PMID 26824423, 2016).
gastric cancer (3 papers, 2020 to 2022). A primary or metastatic malignant neoplasm involving the stomach. "We detected increased expression of FANCD2, TP53BP1, and RPA2 in early gastric cancer, suggesting that DNA damage and DDR are prevalent in the course of this disease." (PMID 36061145, 2022). "All the three subunits RPA1, RPA2, and RPA3, were more abundant (with statistical significance evidence) in lymph node negative and earlier stage (stage I and II) gastric carcinomas." (PMID 36177351, 2022).
bladder cancer (2 papers, 2014 to 2022). "The hub genes of PPI network also indicated broad correlations between GXYLT2 and bladder cancer progression (such as cancer suppressor gene RPA2 and TUSC1." (PMID 36263004, 2022). "In this study, we investigated the mRNA expression of 9 genes (XPB to XPG, ERCC1, RPA1, RPA2)involved in the NER pathway in bladder cancer tissues with/without recurrence, compared with normal bladder cancer tissue." (PMID 25535740, 2014).
Hypertension (2 papers, 2015 to 2018). The presence of chronic increased pressure in the systemic arterial system. "The RPA2-Ab level is weakly associated with age (r2 = 0.113, P < 0.05) with levels significantly higher in those with hypertension (P < 0.05)." (PMID 25890248, 2015).
Obesity (2 papers, 2024 to 2025). Accumulation of substantial excess body fat. "We found that MORC3, NUP62, CGAS, ABI3, and RPA2 were highly expressed in lean individuals, where as LMNA, ID2, CDKN1A, TENT4B, MME, and MYC were upregulated in the PBMCs of individuals with obesity." (PMID 40847086, 2025). "Maternal obesity did not alter quantity of RAD51 and RPA2 foci in leptotene and zygotene oocytes." (PMID 38868907, 2024).
oesophageal cancer (2 papers, 2017 to 2023). "Accordingly, high RPA1 and RPA2 expression levels reportedly increased radioresistance in oesophageal cancer 18 and predicted a poor prognosis in oesophageal cancer 19, colon cancer 20, astrocytic tumours 21 and bladder urothelial cancer." (PMID 28557284, 2017).
oligodendroglioma (2 papers, 2023). A well-differentiated (WHO grade II), diffusely infiltrating neuroglial tumor, typically located in the cerebral hemispheres. "We observe that different genes belonging to this pathway exhibit different trends, for example genes such as POLD1(chr19), RPA2(chr1), and LIG1(chr19) loose a copy in IDH-mut oligodendrogliomas, while genes RPA3(chr19), PMS2(chr19), PCNA(chr20) and POLD2(chr7) gain a copy in IDH-wt GBM." (PMID 36918656, 2023).
osteosarcoma (2 papers, 2012 to 2022). A usually aggressive malignant bone-forming mesenchymal neoplasm, predominantly affecting adolescents and young adults. "In order to detect the presence of the RPA complex in human osteosarcoma U2OS cells by flow cytometry, we initially used two different antibodies raised against the RPA2 subunit of the complex that have been validated in immunofluorescence experiments." (PMID 22893507, 2012).
pancreatic cancer (2 papers, 2021 to 2025). "Furthermore, the identification of RPA2 as a possible driver of the response to PRMT5 inhibition will require further research in pancreatic cancer." (PMID 40723820, 2025).
prostate carcinoma (2 papers, 2025 to 2026). A carcinoma that arises from epithelial cells of the prostate gland. "PCAT19 has been reported to safeguard DNA in quiescent endothelial cells by preventing uncontrolled phosphorylation of replication protein A2 (RPA2), is implicated in driving prostate cancer, and has served as a prognostic biomarker for endometrial cancer." (PMID 40833782, 2025). "Summary-data-based Mendelian Randomization analysis identified significant associations of genetically predicted RPA2 and POLI with prostate cancer risk." (PMID 42216412, 2026). "Our study reveals a genetically inferred causal role for DDR-related genes RPA2 and POLI in prostate cancer risk." (PMID 42216412, 2026). "Immunohistochemical analyses from the human protein atlas database confirmed RPA2 and POLI expression in prostate cancer tissue, while single-cell sequencing data from the tumor immune single-cell hub 2 database indicated differential expression across distinct cellular subpopulations." (PMID 42216412, 2026).
Cluster headache (1 paper, 2024). A type of headache characterized by repeated attacks of unilateral pain lasting 15 to 180 minutes and associated with local autonomic signs. "POLR1B, which encodes DNA-directed RNA polymerase I subunit RPA2, has been linked to Treacher Collins and may be involved in cluster headaches." (PMID 38645487, 2024).
colorectal cancer (1 paper, 2020). A primary or metastatic malignant neoplasm that affects the colon or rectum. "Single nucleotide polymorphisms (SNPs) in miRNA-binding sites in the NER genes RPA2 and GTF2H1 are associated with the risk of colorectal cancer (CRC)." (PMID 32629861, 2020).
esophageal cancer (1 paper, 2023). A primary or metastatic malignant neoplasm involving the esophagus. "Di and colleagues (2014) demonstrated that RPA1 or RPA2 silencing increased the radiosensitivity of radioresistant esophageal cancer cells." (PMID 38137049, 2023).
growth disorder (1 paper, 2022). "Eleven of the 22 analysed CpGs in the genes PDE4C, ELOVL2 and RPA2 exhibited significant differences between young, healthy individuals and age- and sex-matched individuals with growth disorders." (PMID 35551445, 2022).
invasive breast carcinoma (1 paper, 2023). A carcinoma that infiltrates the breast parenchyma. "DCIS and invasive breast cancers showed significantly lower levels of RPA2 compared to normal breast tissue (P < 0.0001)." (PMID 36997566, 2023).
ischemic stroke (1 paper, 2015). A stroke disorder caused by obstruction of blood flow to the brain, due to thrombotic (local blood clot formation) or embolic (due to a blood clot or other material traveling from another site) event. "Further studies are needed to find out whether the elevation of RPA2 Ab could become a biomarker for the evaluation of ischemic stroke at risk." (PMID 25890248, 2015). "RPA2-Abs could become a biomarker for the evaluation of ischemic stroke at risk." (PMID 25890248, 2015). "Therefore, we further analyzed the predictive value of RPA2-Abs for the diagnosis of ischemic stroke." (PMID 25890248, 2015). "Consistently, RPA2 antibody levels were related to ischemic strokes." (PMID 25890248, 2015). "Increasing novel antibody markers identified by SEREX other than RPA2 may improve the predictive accuracy for patients with ischemic stroke." (PMID 25890248, 2015). "ELISA using recombinant antigen proteins and synthetic peptides revealed that the antibody levels to RPA2 were higher in patients with a history of ischemic stroke than in HD, suggesting that the autoimmunity to RPA2 may play some role in the pathogenesis of ischemic stroke." (PMID 25890248, 2015).
multiple endocrine neoplasia type 1 (1 paper, 2023). An autosomal dominant tumor predisposition syndrome caused by pathogenic variants in the MEN1 gene, characterized by an increased risk of tumors of the parathyroid glands, pituitary gland, and foregut neuroendocrine tumors (most commonly pancreatic islet cells). "Menin is tumor suppressor protein, mutated in multiple endocrine neoplasia type 1 syndrome and has been shown to interact with multiple transcription factors including (RPA2) subunit of replication protein A (RPA)." (PMID 37291166, 2023).
muscle atrophy (1 paper, 2024). The loss of muscle tissue due to inactivity or disease. "Previous discussions have linked phosphorylation of RPA2 to spinal muscular atrophy, an autosomal recessive disorder resulting in paralysis and severe muscle atrophy." (PMID 39457877, 2024).